CDCA3 (cell division cycle associated 3)
Diseases named in the same sentence as CDCA3 in open-access papers (continued):
Sharing a sentence is not in itself a finding about the gene and the disease.
prostate carcinoma (10 papers, 2014 to 2025). A carcinoma that arises from epithelial cells of the prostate gland. "Suppression of cell division cycle-associated 3 induced G0/G1-phase arrest to inhibit prostate cancer cell proliferation via cyclin D1 signaling inactivation and p21CIP1 accumulation." (PMID 35246013, 2022). "Clinicopathological features of prostate cancer patients associated with CDCA3 expression." (PMID 37682152, 2023). "Furthermore, overexpression of HOXB3 promotes prostate cancer proliferation through transcriptional activation of cell division cycle associated 3 (CDCA3)." (PMID 29439669, 2018). "But some scholars believe that HOXB3 promotes prostate cancer cell progression by transactivating CDCA3." (PMID 38254070, 2024). "The study was aimed to explore cell division cycle-associated protein-3 (CDCA3) expression and its correlation with clinicopathological characteristics, and identification of co-expressed genes of CDCA3 in prostate cancer (PCa)." (PMID 37682152, 2023). "Another study also found that HoxB3 can bind to the CDCA3 promoter region and transactivate CDCA3 expression to induce prostate cancer progression." (PMID 32716971, 2020). "Previously, CDCA3 was known to be involved in several types of cancer, such as prostate cancer, liver cancer, and oral squamous cell carcinoma." (PMID 29467944, 2018).
renal cell carcinoma (10 papers, 2020 to 2025). "In renal cell carcinomas, SNHG12 was involved in the regulation of the CDCA3 (cell division cycle associated 3) gene mediated by SP1, promoting resistance to sunitinib." (PMID 35406435, 2022). "We first evaluated the effect of CDCA3 on the prognosis of patients with renal cell carcinoma (RCC)." (PMID 36213833, 2022). "SNHG12 promoted tumor progression and sunitinib resistance by upregulating CDCA3 in renal cell carcinoma." (PMID 35721492, 2022). "First, the specific mechanism of CDCA3 on CD8+T cells and its influence on immunotherapy of renal cell carcinoma need to be further explored; second, we have proved that CDCA3 can block the cell cycle, but there is no further study on the biological mechanism." (PMID 36213833, 2022).
liver cancer (7 papers, 2018 to 2024). An epithelial or non-epithelial malignant neoplasm that arises from the liver. "The CDCA3 mRNA was found to be the intracellular target of miR-145, inhibiting proliferation and migration of liver cancer cell lines." (PMID 38890649, 2024). "For liver cancer, recent reports have noticed the tumor-suppressive effects of miR-145-5p in either cholangiocarcinoma or HCC by targeting different mRNAs, like CDCA3, and SPATS2, and involved in cell proliferation, apoptosis, or metastasis." (PMID 36214767, 2022).
lung adenocarcinoma (5 papers, 2020 to 2024). A carcinoma that arises from the lung and is characterized by the presence of malignant glandular epithelial cells. "Cell cycle-related genes (BIRC5, OIP5, and CDCA3, etc.)were specifically upregulated in PTPRT-low lung adenocarcinoma (LUAD)." (PMID 38216925, 2024). "A novel four-gene signature (INPP5B, FOSL2, CDCA3, RASAL2) was established to predict relapse-related survival outcomes in patients with early lung adenocarcinoma after surgery." (PMID 34430085, 2021).
oral cancer (5 papers, 2012 to 2024). "For instance, knockdown of CDCA3 inhibited cellular proliferation by arresting cell-cycle progression at the G1 phase in oral cancer." (PMID 32944002, 2020).
ovarian carcinoma (5 papers, 2020 to 2025). A malignant neoplasm originating from the surface ovarian epithelium. "In the contrast, little is known about the association of CDCA3 and ovarian cancer." (PMID 34577856, 2021). "Previous studies have shown that CDCA3 plays an important role in promoting the development of ovarian cancer." (PMID 38728485, 2024). "A previous report using a microarray data set from 163 tumor types for gene network analysis, demonstrated that CDCA3 was prominently up-regulated in breast, lung, and ovarian cancers relative to that normal tissues." (PMID 33109222, 2020). "The topmost ranked genes uncovered for the PD doublets include CDCA3, PLK1, NEK2 and FAM64A, which are involved in ovarian cancer cell proliferation and drug resistance." (PMID 40280979, 2025). "Further studies are necessary to verify the prognostic value of CDCA3 and UBE2C and to further understand the role of these genes in ovarian cancer to establish them as potential therapeutic targets." (PMID 34577856, 2021).
pancreatic cancer (5 papers, 2019 to 2025). "Many studies have elucidated the role of CDCA3 expression in diverse tumors; for instance, CDCA3 inhibits the formation of tumors by affecting cell growth and inducing apoptosis in pancreatic cancer." (PMID 33604380, 2021).
acute myeloid leukemia (4 papers, 2018 to 2022). Acute myeloid leukemia (AML) is a group of neoplasms arising from precursor cells committed to the myeloid cell-line differentiation. "Further, an in-depth literature analysis revealed that several of these genes play important roles in cancer (CDCA3, ECEL1, EN1, HLA-DMB, SPRR2A, TMEM40) including acute myeloid leukemia (CDCA3, HLA-DMB, RPL18A, PF4, PRG3) and T cell acute lymphoblastic leukemia (TLX3)." (PMID 35008420, 2022).
colon cancer (4 papers, 2021 to 2023). "Several studies have reported that miR-145-5p inhibits colon cancer, for example, miR-145-5p was found to inhibit colon cancer cell proliferation, metastasis, and EMT by targeting CDCA3." (PMID 36960218, 2023).
non-small cell lung carcinoma (4 papers, 2021). A group of at least three distinct histological types of lung cancer, including non-small cell squamous cell carcinoma, adenocarcinoma, and large cell carcinoma. "The expression of CDCA3 in non-small cell lung cancer cells is significantly increased, and is closely related to a poor prognosis." (PMID 34905505, 2021).
oral squamous cell carcinoma (4 papers, 2012 to 2021). "Little is known about the relevance of CDCA3 to human malignancy including oral squamous cell carcinoma (OSCC)." (PMID 22839099, 2012). "Oral squamous cell carcinoma tissues tend to overexpress CDCA1 and CDCA3, which may prevent cellular G1 phase block by inhibiting cyclin-dependent kinase inhibitors." (PMID 34660326, 2021). "Our previous microarray analysis showed that CDCA3, referred to as a trigger of mitotic entry, mediates destruction of mitosis and the inhibitory kinase via the E3 ligase, SCF and was one of the up-regulated genes in the oral squamous cell carcinoma (OSCC)-derived cells." (PMID 22839099, 2012).
glioma (3 papers, 2024 to 2025). A benign or malignant brain and spinal cord tumor that arises from glial cells (astrocytes, oligodendrocytes, ependymal cells). "In summary, this study has demonstrated that high expression of CDCA3 indicates a higher malignancy and poorer prognosis in gliomas, with its mechanism closely linked to the cell cycle." (PMID 38728485, 2024). "CDCA3 is closely associated with many classic glioma biomarkers (CDK4, CDK6), and inhibitors of CDK4 and CDK6 have been shown to be effective in tumor therapy." (PMID 38728485, 2024). "Finally, we visualized the close association between CDCA3 and common glioma cell cycle checkpoint markers, including CDK6, CDK4, CDK2, CDK1, CDKN3, and CDKN2C, using circos plots." (PMID 38728485, 2024). "Similarly, high CDCA3 expression is strongly associated with diminished overall survival (OS) in glioma patients, as evidenced by the CGGA and Rembrandt databases (both yielding P < .0001, respectively)." (PMID 38728485, 2024). "Firstly, we demonstrated the high expression of CDCA3 in gliomas, and its expression level showed a positive correlation with the malignancy of gliomas." (PMID 38728485, 2024). "In order to validate the involvement of CDCA3 in gliomas, we performed Pearson correlation tests independently within 3 distinct databases: TCGA, CGGA, and Rembrandt." (PMID 38728485, 2024). "In this study, bioinformatics analyses (TCGA, CGGA, Rembrandt) shed light on the upregulation and prognostic value of CDCA3 in gliomas." (PMID 38728485, 2024). "Glioma single-cell atlas reveals specific expression of CDCA3, 4, 5, 8 in malignant cells and CDCA7 in neural progenitor cells (NPC)-like malignant cells." (PMID 38181024, 2024). "Our findings indicated that upregulation of CDCA3 is a robust predictor of poor prognosis in glioma patients within the TCGA dataset (P < .0001)." (PMID 38728485, 2024). "We have demonstrated that high expression of CDCA3 indicates a higher malignancy and poorer prognosis in gliomas." (PMID 38728485, 2024). "This study has identified and validated a novel molecular target, CDCA3, for glioma molecular therapy." (PMID 38728485, 2024). "This visualization clearly demonstrates the significant role of CDCA3 within the glioma cell cycle." (PMID 38728485, 2024). "Moreover, an in-depth examination of datasets from both TCGA and CGGA revealed that CDCA3 tends to be more prominently expressed in IDH wild-type gliomas." (PMID 38728485, 2024). "This study investigated the expression of CDCA3 in glioma and its prognostic significance." (PMID 38728485, 2024). "This indicates that CDCA3 plays an important role in the glioma cell cycle." (PMID 38728485, 2024). "Moreover, CDCA3’s molecular functions in gliomas primarily encompass ATPase activity, tubulin binding, helicase activity, microtubule binding, and similar activities." (PMID 38728485, 2024). "Finally, by examining the relationship between CDCA3 and the glioma cell cycle checkpoint, we confirmed the role of CDCA3 in the cell cycle therapy of glioma." (PMID 38728485, 2024). "Furthermore, various methods including GO and GSEA analyses revealed that CDCA3 primarily participates in cell cycle-related functions in gliomas." (PMID 38728485, 2024). "Additionally, we conducted an enrichment analysis to explore the mechanistic role of CDCA3 in glioma." (PMID 38728485, 2024). "To further validate the role of CDCA3 in the glioma cell cycle, we generated a heatmap illustrating the expression of cell cycle-related genes, indicating a positive correlation between CDCA3 and most of these genes in gliomas." (PMID 38728485, 2024). "Simultaneously, the enrichment of CDCA3 in the glioma cell cycle was validated through GSEA." (PMID 38728485, 2024). "Finally, this study suggests that CDCA3 could potentially serve as a biomarker for cell cycle-based therapy in gliomas." (PMID 38728485, 2024).
glioma (continued). "Secondly, through survival analysis, we observed that both glioma and GBM patients with high CDCA3 expression had a poorer prognosis." (PMID 38728485, 2024). "We verified the results of our bioinformatic analysis through Western blot experiment, confirming that CDCA3 gene is highly expressed in GBM, thus affecting the prognosis of glioma patients." (PMID 38728485, 2024). "CDCA2, CDCA3, CDCA4, CDCA5, CDCA7, and CDCA8 were significantly highly expressed in glioma samples." (PMID 38181024, 2024).
leukemia (3 papers, 2018 to 2022). A malignant (clonal) hematologic disorder, involving hematopoietic stem cells and characterized by the presence of primitive or atypical myeloid or lymphoid cells in the bone marrow and the blood. "In leukemia cell lines, miR-375 expression is down-regulated, and miR-375 inhibits CDCA3 expression by downregulating HOXB3 expression, thereby suppressing cell proliferation." (PMID 34905505, 2021). "Importantly, some of these genes have already been reported in relation to CML (e.g., AURKB, AZU1, HLA-B, HLA-DMB, PF4) and others have been found to play important roles in different leukemias (e.g., CDCA3, RPL18A, PRG3, TLX3)." (PMID 35008420, 2022). "Next, we determined whether knockdown of CDCA3 presents anti-leukemia activity." (PMID 29439669, 2018).
bladder urothelial carcinoma (2 papers, 2021). "A GSEA analysis also demonstrated that CDCA3 mainly functioned by regulating the cell cycle process in bladder urothelial carcinoma." (PMID 33980246, 2021). "As our data have demonstrated that CDCA3 played a significant role in regulating the cell cycle, we used flow cytometry to validate this function of CDCA3 in bladder urothelial carcinoma cells." (PMID 33980246, 2021). "The transwell assay demonstrated that the migration ability of bladder urothelial carcinoma cells was significantly impaired when CDCA3 was knocked down." (PMID 33980246, 2021). "We designed two specific CDCA3 target siRNAs to transfect 5637 and T24 bladder urothelial carcinoma cell lines." (PMID 33980246, 2021). "Next, we decided to explore how CDCA3 functions as an oncogene in human bladder urothelial carcinoma." (PMID 33980246, 2021). "CDCA3 expression was significantly up-regulated in bladder urothelial carcinoma, cervical squamous cell carcinoma and adenocarcinoma, KIRP, KIRC, and other cancer types." (PMID 34905505, 2021). "Chi square test for the correlation between CDCA3 and clinical characteristics of bladder urothelial carcinoma patients from TCGA database showed that the expression level of CDCA3 was highly related to tumor grade." (PMID 33980246, 2021). "The results showed that CDCA3 demonstrated a significantly high expression in the whole samples, and in the matched pairs, the mRNA level of CDCA3 was also higher in bladder urothelial carcinoma tissues than in normal tissues." (PMID 33980246, 2021). "Bioinformatic analysis revealed that CDCA3 was significantly up-regulated in bladder urothelial carcinoma samples and was related to key clinical characteristics, such as tumor grade and metastasis." (PMID 33980246, 2021). "These two assays revealed that the motility of bladder urothelial carcinoma cells was strongly impaired after the silencing of CDCA3 and indicated that the potential of CDCA3 in promoting the distant metastasis of bladder urothelial carcinoma." (PMID 33980246, 2021). "Bioinformatic methods were used to analyze the expression level of CDCA3 in human bladder urothelial carcinoma tissues and the relationship between its expression level and key clinical characteristics." (PMID 33980246, 2021). "Collectively, we demonstrated that CDCA3 played an oncogenic role through regulating cell cycle and mitosis in human bladder urothelial carcinoma." (PMID 33980246, 2021). "Our analysis results demonstrated that the expression level of CDCA3 mRNA was obviously up-regulated in 18 types of human cancer, including bladder urothelial carcinoma." (PMID 33980246, 2021). "In our present research, we comprehensively analyzed the expression status of CDCA3 in bladder urothelial carcinoma tissues and the relationship between its expression level and key clinical characteristics." (PMID 33980246, 2021). "Our study demonstrated that CDCA3 is a novel potential biomarker of human bladder urothelial carcinoma." (PMID 33980246, 2021). "Based on the analysis of expression profile data of bladder urothelial carcinoma, members of our laboratory have identified several potential biomarkers correlated to the TNM stage and OS of bladder urothelial carcinoma patients, which included CDCA3." (PMID 33980246, 2021). "After the preliminary exploration of the bio-function of CDCA3, we tried to further the specific role of the oncogene in promoting bladder urothelial carcinoma." (PMID 33980246, 2021). "In vivo study confirmed that silencing CDCA3 could inhibit the proliferation of bladder urothelial carcinoma cells." (PMID 33980246, 2021). "As we preliminary demonstrated that CDCA3 might be related to distant metastasis of bladder urothelial carcinoma, two migration ability assays were performed to test whether it affected promoting tumor cell migration." (PMID 33980246, 2021). "Therefore, we conducted a series of experiments to explore the role of CDCA3 in bladder urothelial carcinoma." (PMID 33980246, 2021).
bladder urothelial carcinoma (continued). "The cell viability and colony formation assay were conducted to examine whether decreased expression of CDCA3 could slow down the proliferation rate of bladder urothelial carcinoma cells." (PMID 33980246, 2021). "CDCA3 is an important oncogene that could strengthen the migration ability of bladder urothelial carcinoma cells and accelerate tumor cell growth via regulating cell cycle progress and is a potential biomarker of bladder urothelial carcinoma." (PMID 33980246, 2021). "In this part, we constructed two efficient siRNAs to silence the expression of CDCA3 and subsequent tumor proliferation-related experiments showed that CDCA3 could promote the growth of bladder urothelial carcinoma." (PMID 33980246, 2021). "In our present study, we demonstrated that CDCA3 was correlated to bladder urothelial carcinoma progression and could be a novel predictor for bladder urothelial carcinoma patients." (PMID 33980246, 2021). "Data in GSE13507 verified that CDCA3 was elevated in bladder urothelial carcinoma tissues and demonstrated that patients with shorter survival span tended to present a higher CDCA3 level which showed that CDCA3 was also a potential predictor of bladder urothelial carcinoma." (PMID 33980246, 2021). "Thus a transwell assay and wound healing assay were performed to validate the role of CDCA3 in promoting the migration ability of bladder urothelial carcinoma cells." (PMID 33980246, 2021). "CDCA3 is an important oncogene that could strengthen the invasive and migrate ability of bladder urothelial carcinoma and accelerate tumor cell growth via promoting the transition from G1 to S phase in bladder urothelial carcinoma." (PMID 33980246, 2021). "A series of functional experiments confirmed that CDCA3 could promote the migration ability of bladder urothelial carcinoma cells and could accelerate cell growth by promoting the course of the cell cycle." (PMID 33980246, 2021). "Moreover, as for the clinical characteristics, we found a higher mRNA level of CDCA3 in high grade bladder urothelial carcinoma tissues, indicating the potential role of CDCA3 in bladder urothelial carcinoma development." (PMID 33980246, 2021). "In a word, silencing CDCA3 expression could inhibit the growth ability of bladder urothelial carcinoma cells in vivo." (PMID 33980246, 2021). "Next, we chose to examine the correlation of the level of CDCA3 with crucial clinical characteristics in bladder urothelial carcinoma, such as tumor grade, tumor distant metastasis, and the overall survival rate of bladder urothelial carcinoma patients." (PMID 33980246, 2021). "Moreover, as the expression level is closely correlated to the overall life span of bladder urothelial carcinoma patients, CDCA3 exhibited the potential to be a novel biomarker of bladder urothelial carcinoma." (PMID 33980246, 2021). "Moreover, the expression level of key EMT-related proteins such as N-Cad, MMP9, Vimentin, Slug and Snail were correspondingly decreased, which indicated us that the up-regulated CDCA3 could participate in the EMT process of bladder urothelial carcinoma." (PMID 33980246, 2021). "Also, CDCA3 was up-regulated in tissues with distant metastasis, suggesting that CDCA3 may participate in the epithelial-to-mesenchymal transition (EMT) process in bladder urothelial carcinoma." (PMID 33980246, 2021). "In conclusion, in this part, we uncovered that CDCA3 was significantly elevated in human bladder urothelial carcinoma tissues, positively correlated to key clinical characteristics, and could be a predictive biomarker of bladder urothelial carcinoma." (PMID 33980246, 2021). "CDCA3 has been widely identified as a proto-oncogene in multiple human cancers, however, its role in promoting human bladder urothelial carcinoma has not been fully elucidated." (PMID 33980246, 2021). "However, researches about the function of CDCA3 in promoting bladder urothelial carcinoma development and progression are still absent." (PMID 33980246, 2021).